MXD1 (MAX dimerization protein 1)
Description:
Component of a transcriptional repressor complex together with MAX. In complex with MAX binds to the core DNA sequence 5'-CAC[GA]TG-3'. Antagonizes MYC transcriptional activity by competing with MYC for MAX binding. Binds to the TERT promoter and represses telomerase expression, possibly by interfering with MYC binding.
Synonyms: MAD; MAD1; bHLHc58
Tractability: PROTAC: UniProt records ubiquitination sites on it; ubiquitination databases record sites on it.
Gene: Protein-coding gene on chromosome 2 (69,897,688 to 69,942,945, forward strand). Ensembl gene ENSG00000059728.
Subcellular location: Nucleus
Subcellular location (Human Protein Atlas): Mitochondria; Nucleoplasm; Cytosol
Gene Ontology:
Molecular function: DNA-binding transcription repressor activity, RNA polymerase II-specific; protein binding; RNA polymerase II cis-regulatory region sequence-specific DNA binding; DNA-binding transcription factor activity, RNA polymerase II-specific; protein dimerization activity
Biological process: negative regulation of transcription by RNA polymerase II; regulation of transcription by RNA polymerase II
Cellular component: chromatin; Mad-Max complex; nucleus; RNA polymerase II transcription repressor complex
Genetic constraint (gnomAD): Loss-of-function variants: 5 observed, 15.01 expected, observed/expected ratio (o/e) 0.33, 90% interval 0.17 to 0.7. The upper end of that interval is the gene's LOEUF score, 0.7, which puts it in group 2 of 6, group 1 being the genes least tolerant of losing a copy. Missense variants: 179 observed, 203.1 expected, observed/expected ratio (o/e) 0.88, 90% interval 0.78 to 1. Synonymous variants: 78 observed, 82.29 expected, observed/expected ratio (o/e) 0.95, 90% interval 0.79 to 1.14.
Homologues: Orthologues: chimpanzee MXD1 (100% identical), macaque MXD1 (99% identical), guinea pig MXD1 (98% identical), pig MXD1 (95% identical), rabbit MXD1 (95% identical), rat Mxd1 (89% identical), mouse Mxd1 (88% identical), tropical clawed frog mxd1 (81% identical), dog MXD1 (77% identical), zebrafish mxd1 (71% identical), Caenorhabditis elegans mdl-1 (31% identical). Paralogues in human: MXI1 (56% identical), MXD4 (50% identical), MXD3 (41% identical), MNT (28% identical).
Diseases named in the same sentence as MXD1 in open-access papers:
MXD1 is named in the same sentence as 40 diseases in open-access papers, as found by Europe PMC text mining. Sharing a sentence is not in itself a finding about the gene and the disease. The quoted sentences say what the papers report.
gastric cancer (9 papers, 2013 to 2025). A primary or metastatic malignant neoplasm involving the stomach. "Reduced MXD1 levels have been associated with increased cell survival and invasiveness in cancers, including pancreatic, breast, and gastric cancers." (PMID 40958908, 2025). "The role of ATF3 in colorectal cancer is yet to be determined, but the tumor suppressor MXD1 was deciphered to be targeted by MiR-19a/b in gastric cancer." (PMID 34831349, 2021). "miR-19a/b, members of the miR-17-92 cluster, promote gastric cancer cell migration, invasion and metastasis by targeting MXD1, which acts as an antagonist of the c-Myc oncoprotein." (PMID 29861871, 2018). "For example, miR-19a was reported to play oncogenic role in gastric cancer by targeting the tumor suppressor MXD1,in cervical carcinoma by targeting CUL5 and in pancreatic cancer by downregulating RHOB promote and." (PMID 29416742, 2018).
melanoma (5 papers, 2017 to 2025). A malignant, usually aggressive tumor composed of atypical, neoplastic melanocytes. "Intriguingly, while SIRT1 was shown to regulate c-MYC in Flt3-ITD mutated leukemia, it has been demonstrated to regulate Mxd1 in malignant melanoma." (PMID 30420889, 2018). "We also found that the preferential induction by corin vs. MS-275 of CHOP and MXD1 was abolished in the CoREST knockdown melanoma cells." (PMID 29302039, 2018). "MYC/MAX/MXD1 network has been shown to play a major role in the development of neuroblastoma and melanoma." (PMID 29383100, 2017). "Corresponding to this, treatment of cells with DNMT inhibitor led to a continuous increase in Mxd1 expression along melanoma progression, suggesting sequential acquisition of aberrant epigenetic marks." (PMID 29383100, 2017). "Sirt1 stable silencing increased Mxd1 mRNA expression and led to down-regulation of MYC targets, such as Cdkn1a, Bcl2 and Psen2, whose upregulation is associated with human melanoma aggressiveness and poor prognosis." (PMID 29383100, 2017). "The Mxd1 expression decreased along melanoma progression, being significantly reduced in pre-malignant 4C melanocytes and both non-metastatic 4C11- and metastatic 4C11+ tumor cell lines compared with parental melan-a melanocytes." (PMID 29383100, 2017). "Our data indicate that SIRT1 and DNMT3B co-participate in Mxd1 epigenetic silencing in melanoma." (PMID 29383100, 2017). "In melanoma cells, SIRT1 silences MXD dimerization protein 1 (Mxd1) by binding to DNMT3B, thereby increasing resistance to dead-cancer-induced stress, which leads to increased Myc activity and drives melanoma progression." (PMID 39479446, 2024). "SIRT1 promoted Mxd1 silencing, which led to increased activity of MYC oncogene contributing to melanoma progression." (PMID 29383100, 2017). "Since in our model SIRT1 represses Mxd1 gene expression, we suggest that MYC is activated in melanoma progression." (PMID 29383100, 2017). "Depending on the ROS-induced DNA damage, the SIRT1 relocation at Mxd1 sequence and stress-induced SIRT1 recruited repressive protein complexes might vary along the different steps of melanoma progression." (PMID 29383100, 2017). "Considering the reversibility of epigenetic changes, the participation of SIRT1 and other epigenetic components in reducing Mxd1 expression and in increasing MYC oncogenic activity might have prognostic and therapeutic potential in melanoma." (PMID 29383100, 2017). "Sirt1 silencing increased expression of Mxd1 in both cell lines compared to non-silenced cells, pointing to a Mxd1 repression by SIRT1 in melanoma cells." (PMID 29383100, 2017). "Since Mxd1 is downregulated by SIRT1 in 4C11- and 4C11+ tumor cell lines, we have postulated that MAX could become more available to MYC binding in these melanoma cells." (PMID 29383100, 2017). "Surprisingly, the ChIP assay along melanoma progression stages did not confirm this interaction in pre-malignant 4C melanocytes, but SIRT1/Mxd1 interaction was remarkably evident at later stages." (PMID 29383100, 2017).
leukemia (3 papers, 2016 to 2022). A malignant (clonal) hematologic disorder, involving hematopoietic stem cells and characterized by the presence of primitive or atypical myeloid or lymphoid cells in the bone marrow and the blood. "The levels of MXD1 mRNA transcripts ranked the lowest in colorectal cancer (13 studies), leukemia (8 studies), esophageal cancer (5 studies) and head and neck cancer (4 studies)." (PMID 36167790, 2022). "Nucleolar localization of endogenous MXD1 was observed in growing cells from different tissues origins (carcinoma, leukemia, embryonic stem cells) as well as in primary post-mitotic cells as neurons and Sertoli cells." (PMID 27588501, 2016). "Here we describe that MXD1, but not MYC or MNT, localizes to the nucleolus in a wide array of cell lines derived from different tissues (carcinoma, leukemia) as well as in embryonic stem cells." (PMID 27588501, 2016).
lymphoma (3 papers, 2016 to 2021). A malignant (clonal) proliferation of B- lymphocytes or T- lymphocytes which involves the lymph nodes, bone marrow and/or extranodal sites. "In this study, we report that NL101 is highly active against B cell lymphomas such as DLBCL and BL, and NL101 significantly inhibits the expression of miR-21, which promotes lymphoma cell survival through modulating c-Myc/Mxd1 axis." (PMID 33537096, 2021). "Here again, expression of cFOS, MXD1, JUNB, cJUN, and DUSP1 was significantly higher (3.7 fold, 7.1 fold, 3.1 fold, 3.4 fold and 9.1 fold, respectively) in lymphomas with high cytoplasmic NR4A1 content (p < 0.036)." (PMID 30266952, 2018).
pancreatic cancer (3 papers, 2017 to 2025). "For instance, resistance in hepatocellular carcinoma involves the p-MYH9/USP22 axis stabilizing HIF-1alpha, promoting stemness and lenvatinib resistance, while in pancreatic cancer, targeting MXD1 overcomes trametinib resistance." (PMID 40696490, 2025).
B cell lymphoma (2 papers, 2021 to 2022). "It is therefore likely that blocking c-Myc/Mxd1 axis serves as a novel strategy to target aberrant c-Myc function, which remains to be explored in B cell lymphomas." (PMID 33537096, 2021). "Taken together, we revealed c-Myc/miR-21/Mxd1 as a novel positive-feedback loop that plays a critical role in the maintenance of B cell lymphoma." (PMID 33537096, 2021). "The novel c-Myc/miR-21/Mxd1 positive-feedback loop is critical for the maintenance of B cell lymphoma survival." (PMID 33537096, 2021). "Through the significant inhibition of miR-21 expression, NL101 efficiently blocks the c-Myc/miR-21/Mxd1 positive feedback loop, which is critical for the survival of B cell lymphoma." (PMID 33537096, 2021). "MXD1 is a transcription factor that belongs to the MYC/MXD/MAX family, and is implicated in the pathophysiology of avian influenza virus infections, intracerebral hemorrhage, and various cancers such as osteosarcoma, lung adenocarcinoma and B cell lymphoma." (PMID 35609226, 2022). "Indeed, c-Myc directly activates miR-21 transcription, and miR-21 targets Mxd1 to enhance c-Myc transcriptional activity, leading to sustained high levels of miR-21 and c-Myc in aggressive B cell lymphoma." (PMID 33537096, 2021). "Thus, c-Myc/miR-21/Mxd1 represents a novel positive feedback loop that plays an essential regulatory role in the survival of B cell lymphoma." (PMID 33537096, 2021). "By targeting miR-21 to block c-Myc/miR-21/Mxd1 axis, NL101 shows its promise as an anticancer agent for B cell lymphoma treatment in the future." (PMID 33537096, 2021). "In this study, we found that c-Myc, miR-21 and Mxd1 form a positive-feedback loop, which is pro-survival for B cell lymphoma; NL101, a DNA/HDAC dual-targeting small compound 18, 19, can effectively inhibit the growth of B cell lymphoma through blocking c-Myc/miR-21/Mxd1 loop." (PMID 33537096, 2021).
esophageal squamous cell carcinoma (2 papers, 2022 to 2025). Esophageal squamous cell carcinoma (ESCC) is a type of esophageal carcinoma (EC) that can affect any part of the esophagus, but is usually located in the upper or middle third. "MXD1 has been identified as a potential biomarker associated with specific molecular changes and tumor microenvironment characteristics in esophageal squamous cell carcinoma, but biological functions in psoriasis or immunology have been less reported." (PMID 40560938, 2025). "Low MXD1 mRNA expression levels were reported in patients with esophageal squamous cell carcinoma." (PMID 36430806, 2022).
glioma (2 papers, 2025 to 2026). A benign or malignant brain and spinal cord tumor that arises from glial cells (astrocytes, oligodendrocytes, ependymal cells). "The subcutaneous and orthotopic glioma xenograft models in nude mice were used to elucidate the inhibitory effects of the TRMT10A/tRF-22/MXD1 pathway on glioma." (PMID 40140670, 2025). "Western blot confirmed that MXD1 expression was significantly downregulated in glioma cells transfected with tRF-22 mimic and upregulated in those transfected with tRF-22 inhibitor." (PMID 40140670, 2025). "Furthermore, RT-qPCR and Western blot analyses were performed to assess MXD1 expressions in human astrocytes and glioma cells." (PMID 40140670, 2025). "Overexpression of tRF-22 in glioma cells significantly downregulates MXD1 expression." (PMID 40140670, 2025). "MXD1 overexpression in glioma cells markedly suppressed glioma VM formation." (PMID 40140670, 2025). "tRF-22 negatively regulates MXD1 expression by binding to the 3’UTR of MXD1 mRNA, thereby diminishing MXD1’s transcriptional repression of the HIF1A gene and promoting glioma VM formation." (PMID 40140670, 2025). "tRF-22 negatively regulates MXD1 expression by binding to its 3’UTR, reducing MXD1’s transcriptional inhibition of HIF1A, thereby promoting glioma cell proliferation, migration, invasion, and tube formation." (PMID 40140670, 2025). "tRF-22 negatively regulates the transcription factor MXD1 expression, diminishing its transcriptional repression of the HIF1A gene, thus promoting VM formation in gliomas." (PMID 40140670, 2025). "tRF-22 negatively regulates MAX dimerization protein 1 (MXD1) expression by binding to its 3′UTR, thereby weakening MXD1's transcriptional suppression of hypoxia-inducible factor 1 alpha (HIF1A) and promoting glioma vascular mimicry (VM) formation." (PMID 41550494, 2026). "Analysis of the HIF1A gene promoter region revealed the presence of the MXD1 recognition motif 5’-CACGTG-3’, suggesting MXD1 may negatively regulate HIF-1α expression and modulate VM formation in gliomas." (PMID 40140670, 2025).
lung adenocarcinoma (2 papers, 2021 to 2022). A carcinoma that arises from the lung and is characterized by the presence of malignant glandular epithelial cells. "For example, Xu and Chen utilized a six AG-based pattern (APOC3, EPOR, H2AFX, MXD1, PLCG2, and YWHAZ) to structure a risk model that could efficiently stratify the existing cases in high- and low-risk groups in terms of OS in lung adenocarcinoma (LUAD)." (PMID 34976839, 2021).
lung carcinoma (2 papers, 2020 to 2021). "However, the roles of MXD1 in lung cancer remain largely unexplored." (PMID 34277626, 2021).
osteosarcoma (2 papers, 2018 to 2022). A usually aggressive malignant bone-forming mesenchymal neoplasm, predominantly affecting adolescents and young adults. "For example, HIF-1α-induced MAX dimerization protein 1 upregulation contributed to hypoxia-induced DDP resistance in osteosarcoma cells through activation of the PI3K/Akt pathway." (PMID 29898734, 2018).
ovarian carcinoma (2 papers, 2020 to 2021). A malignant neoplasm originating from the surface ovarian epithelium. "Restoration of MAGI2-AS3 expression in the human ovarian cancer SUN8 and Caov3 cell lines depletes miR-525-5p which exhausts MXD1 (MAX dimerization protein 1)." (PMID 34503076, 2021).
Burkitt lymphoma (1 paper, 2021). A rare form of malignant mature B-cell non-Hodgkin lymphoma. "The human lymphoid cell line P493–6 and the Burkitt’s lymphoma cell line RAMOS were transduced with lentiviral vectors to stably express dCas9 fused with the SIN3 interacting domain of MXD1 (MAX Dimerization Protein 1)." (PMID 34199901, 2021).
cholangiocarcinoma (1 paper, 2022). A carcinoma that arises from the intrahepatic biliary tree (intrahepatic cholangiocarcinoma) or from the junction, or adjacent to the junction, of the right and left hepatic ducts (hilar cholangiocarcinoma). "However, there is no information on whether HOXA5 can regulate MXD1 expression and its downstream signaling in cholangiocarcinoma." (PMID 36167790, 2022).
metastatic melanoma (1 paper, 2017). A melanoma that has spread from its primary site to another anatomic site. "In addition, Mxd1 was found downregulated from pre-malignant melanocytes to metastatic melanoma cells." (PMID 29383100, 2017).
metastatic prostate carcinoma (1 paper, 2017). A carcinoma that arises from the prostate gland and has spread to other anatomic sites. "Data sets with significant down regulation of PrKD1 in metastatic prostate cancer were identified, and the gene expression data for MYC, MAX and MXD1 were compared." (PMID 29108267, 2017).
oral cancer (1 paper, 2021). "Moreover, four genes (SERPINB2, GFOD1, TGFA, MXD1) were downregulated in these samples suggesting an inhibitory role in oral cancer cell invasion and metastasis." (PMID 34116687, 2021).
preeclampsia (1 paper, 2023). Preeclampsia is a hypertensive disorder of pregnancy that is characterized by new-onset hypertension with proteinuria presenting after 20 weeks of gestation, and depending on mild or severe forms may initially present with severe headache, visual disturbances, and hyperreflexia. "SKAP2 was downregulated in the villous tissues of patients with failed pregnancies, while MXD1 was associated with early and late gestation in patients with severe preeclampsia." (PMID 36833425, 2023).
prostate carcinoma (1 paper, 2021). A carcinoma that arises from epithelial cells of the prostate gland. "Higher levels of JUN, MXD1, and AQP3 were associated with a better OS, and each of the three genes was upregulated by deslanoside, suggesting that JUN, MXD1, and AQP3 could mediate deslanoside’s anticancer effect in prostate cancer cells." (PMID 34830961, 2021).
prostate tumor (1 paper, 2022). "Presumably, prostate tumor cells that have lost the ability to express functional MXD1 or RGS4 would lose the capacity to enforce these observed Poly E-mediated antiproliferative effects on PC-3 cells, and perhaps other PCa cells as well." (PMID 36430806, 2022).
psoriasis (1 paper, 2025). An autoimmune condition characterized by red, well-delineated plaques with silvery scales that are usually on the extensor surfaces and scalp. "In addition, 8 genes (DEFB103A, OASL, HERC6, ISG15, MKI67, MX1, MXD1, SCO2) were considered to have statistically significant differences in sensitivity of short-term treatment for psoriasis." (PMID 40560938, 2025).
ZIKV infection (1 paper, 2022). "Accordingly, our data demonstrated an increased MXD1 gene expression by ZIKV infection, a transcriptional repressor of Myc transcriptional activity and a target of all downregulated miRNAs." (PMID 36142200, 2022).